Y_RNA (Y RNA )
Gene: Miscellaneous RNA gene on chromosome 8 (97,772,313 to 97,772,425, forward strand). Ensembl gene ENSG00000202399.
Homologues: Orthologues: chimpanzee Y_RNA (99% identical), macaque Y_RNA (96% identical). Paralogues in human: RNY1 (87% identical), Y_RNA (86% identical), Y_RNA (84% identical), Y_RNA (83% identical), Y_RNA (82% identical), RNY1P11 (81% identical), Y_RNA (81% identical), RNY1P8 (80% identical), Y_RNA (80% identical), RNY1P10 (79% identical), RNY1P12 (79% identical), RNY1P7 (79% identical), and 95 more.